POLR1H (RNA polymerase I subunit H)
Description:
Core component of RNA polymerase I (Pol I), a DNA-dependent RNA polymerase which synthesizes ribosomal RNA precursors using the four ribonucleoside triphosphates as substrates. Can mediate Pol I proofreading of the nascent RNA transcript. Anchors into the Pol I active site to monitor transcription fidelity and cleave mis-incorporated 5'-ribonucleotides.
Synonyms: RPA12; ZNRD1; hZR14; HTEX-6; tctex-6; A12.2; HTEX6; TCTEX6; TEX6; ZR14
Tractability: Small molecule: a structure with a bound ligand is known.
Gene: Protein-coding gene on chromosome 6 (30,058,899 to 30,064,909, forward strand). Ensembl gene ENSG00000066379.
Subcellular location: Nucleus, nucleolus
Subcellular location (Human Protein Atlas): Nucleoli fibrillar center
Pathways (Reactome):
Gene expression (Transcription): B-WICH complex positively regulates rRNA expression; NoRC negatively regulates rRNA expression; RNA Polymerase I Promoter Escape; RNA Polymerase I Transcription Initiation; RNA Polymerase I Transcription Termination
Gene Ontology:
Molecular function: protein binding; DNA-directed RNA polymerase activity; nucleic acid binding; zinc ion binding
Biological process: transcription elongation by RNA polymerase I; nucleobase-containing compound metabolic process; nucleolar large rRNA transcription by RNA polymerase I; termination of RNA polymerase I transcription; transcription initiation at RNA polymerase I promoter; DNA-templated transcription
Cellular component: fibrillar center; RNA polymerase I complex; nucleoplasm; nucleus; nucleolus
Genetic constraint (gnomAD): Loss-of-function variants: 3 observed, 13.63 expected, observed/expected ratio (o/e) 0.22, 90% interval 0.099 to 0.57. The synonymous counts are far from expectation, so gnomAD's model fits this gene poorly and the ratio says little. Missense variants: 97 observed, 164.31 expected, observed/expected ratio (o/e) 0.59, 90% interval 0.5 to 0.7. Synonymous variants: 41 observed, 60.12 expected, observed/expected ratio (o/e) 0.68, 90% interval 0.53 to 0.88.
Homologues: Orthologues: chimpanzee POLR1H (100% identical), macaque POLR1H (94% identical), pig POLR1H (87% identical), rat Polr1h (83% identical), mouse Polr1h (80% identical), dog POLR1H (78% identical), guinea pig POLR1H (68% identical), tropical clawed frog polr1h (63% identical), zebrafish polr1h (53% identical), Caenorhabditis elegans rpoa-12 (39% identical), Drosophila melanogaster Polr1H (36% identical). Paralogues in human: POLR3K (24% identical), POLR2I (17% identical).
Diseases named in the same sentence as POLR1H in open-access papers:
POLR1H is named in the same sentence as 24 diseases in open-access papers, as found by Europe PMC text mining. Sharing a sentence is not in itself a finding about the gene and the disease. The quoted sentences say what the papers report.
bladder cancer (2 papers, 2022 to 2023). "We constructed a prognostic model based on Necroptosis subtype-related prognosis DEGS by lasso algorithm and multivariate COX analysis, which consists of 6 predictors (CERCAM POLR1H, KCNJ15, GSDMB, EHBP1, TRIM38), among which CERCAM is closely related to bladder cancer." (PMID 35478725, 2022).
POLR1H also shares sentences with these, for which no sentence is quoted: gastric cancer (7 papers); AIDS (5); breast carcinoma (5); cancer (5); leukemia (4); tumor (4); hepatocellular carcinoma (3); infection (3); esophageal squamous cell carcinoma (2); HIV-1 infection (2); osteosarcoma (2); Anxiety (1); cardiac hypertrophy (1); esophageal cancer (1); glioblastoma (1); ischemic stroke (1); lymph node metastasis (1); Miscarriage (1); prostate carcinoma (1); prostate tumor (1); renal cell carcinoma (1); schizophrenia (1); virus infection (1).